CD47 (CD47 molecule)
Diseases named in the same sentence as CD47 in open-access papers (continued):
Sharing a sentence is not in itself a finding about the gene and the disease.
tumor (continued). "The results revealed that under fluorescence microscopy, specific fluorescence signals were observed on tumor cells, and CD47 was predominantly located on the membrane of these tumor cells, whereas no significant fluorescent signals were seen on the normal endometrial tissues adjacent to the cancer." (PMID 40385528, 2025). "This activation is associated with c‐Myc‐mediated cluster of differentiation 47 (CD47) transcription, where CD47 upregulation may inhibit macrophage phagocytosis of tumor cells, inhibiting programmed cell death." (PMID 39802639, 2025). "The piezo-catalytic effect generated by ultrasound stimulation not only induces ICD but also significantly enhances the phagocytosis of tumor cells by macrophages, reducing the “don’t eat me” signal (CD47) on the surface of tumor cells through inhibition of N-glycosylation." (PMID 41472729, 2025). "Engineered exosomes, such as GEMINI-Exos armed with anti-CD3, anti-EGFR, PD-1, and OX40L, have demonstrated significant inhibition of triple-negative breast cancer in mice, while surface modifications like PEGylation or CD47 overexpression enhance circulation and tumour targeting." (PMID 41181109, 2025). "Hence, after establishing the CAR-Ms platform, we explored a combination strategy involving oAd-CD47 nanoantibody with CAR-Ms for tumor treatment." (PMID 40814015, 2025). "Using a rigorously calibrated mathematical model informed by in vivo data, we identify an optimal RT dose range (6 to 8 Gy) that maximizes ICD and reveal that SIRPα-CD47 checkpoint inhibition transforms radiation-induced tumor cell death into a potent systemic immune stimulus." (PMID 41296731, 2025). "Additionally, the IHC results revealed that the Vpr peptide vaccine led to upregulation of CD47 expression in the distant tumor." (PMID 40733687, 2025). "However, tumor cells overexpress Cluster of Differentiation 47 (CD47) to evade macrophage-mediated phagocytosis." (PMID 41280655, 2025). "Therefore, design of novel CD47 blockers should aim to mitigate these risks in addition to facilitating phagocytosis of tumor cells." (PMID 40078999, 2025). "Importantly, the combined CD47 antibody with rapamycin significantly enhanced anti‐tumor immunotherapy." (PMID 39665172, 2025). "DMPLAC/siCD47 efficiently reduced the expression of CD47 in the tumor tissues." (PMID 40006507, 2025). "While anti-CD47 antibodies restore tumor clearance, they also deplete CAR-T cells." (PMID 41511353, 2025). "Thirdly, the presence of a distinct cluster of SIRPα+ macrophages suggests that at least some phagocytic cells would be prone to stimulation by tumour-expressed CD47, thereby making them incapable of engulfing abnormal cellular bodies and limiting their anti-tumour role." (PMID 40870972, 2025). "In addition to this, the expression of CD47 on non-tumor cells, like ECs, is crucial in regulating tumor angiogenesis." (PMID 41300494, 2025). "Therefore, radiotherapy combined with anti-CD47 not only promotes tumor cells sensitivity to radiotherapy but also has radioprotective effects on normal tissues and organs." (PMID 40835598, 2025). "Similarly, our preclinical model suggests that the alternative approach of targeting SMYD3 to affect CD47 signaling combined with a PD‐1 inhibitor results in increased tumor suppression in ccRCC." (PMID 40548645, 2025). "Interestingly, another recent study found that the simultaneous blockade of PD-L1 and CD47 with radiotherapy promoted the abscopal effect mediated by improving macrophage phagocytosis of damaged tumor cells, as well as CD8+ T cell activation." (PMID 41375050, 2025). "Considering the clinical limitations of current CAR-T cell therapy in the treatment of solid cancers, the combination strategy of CAR-M cell therapy with oAd-CD47 may be an effective approach for personalized tumor-specific oncolytic immunotherapy." (PMID 40814015, 2025). "Small‐molecule inhibitors of LAT2 reportedly inhibit CD47‐mediated tumor immune escape." (PMID 39778021, 2025).
tumor (continued). "It was found that CD47 absence markedly improved anti-tumor efficacy mediated by anti-PD-1 therapy." (PMID 40861801, 2025). "Therefore, we further established the LLC bilateral subcutaneous tumor model to evaluate the anti-tumor effects of Vpr peptide combined with SIRPαFc, a fusion protein for CD47 blockade therapy." (PMID 40733687, 2025). "Besides, the CD47/TSP-1 axis is also gaining much attention for its promoting effects on tumor survival and cancer stem cell differentiation, and inhibitory effects on anti-tumor immunity and therapy sensitivity." (PMID 40830526, 2025). "The PLGA-CpG@ID8-M nanovaccine overcomes free CpG accumulation, reprograms TAMs to tumoricidal M1 macrophages via Gbp2/Pin1–NFκB signaling, inhibits tumor growth, and counteracts chemotherapy-induced immunosuppression by boosting M1 TAMs and lowering tumor CD47." (PMID 41280929, 2025). "Recent studies have developed magnetically guided nanosystems by covalently conjugating anti-CD47 antibodies onto the surface of silica-coated IONPs, enabling their enrichment at metastatic tumor sites and effectively blocking the interaction between tumor cell-expressed CD47 and macrophage SIRPα." (PMID 41280655, 2025). "Also, anti-CD47 can enhance tumor cells sensitivity to radiotherapy by inhibiting tumor pluripotency capabilities and reducing the expression of DNA repair enzymes in OSCC." (PMID 40835598, 2025). "Therefore, CD47 blockade is essential for liberating the anti-tumor capacity of macrophages upon HDACi therapies." (PMID 39994810, 2025). "Our analysis also highlights significant correlations between CD47 expression and clinicopathologic features, including age (≥ 60 years old), TNM staging, lymph node metastasis, tumor differentiation, and tumor recurrence, providing new insights into the prognostic value of CD47." (PMID 40765033, 2025). "Therefore, a simultaneous increase in pro-phagocytic surface CRT and decrease in CD47 would suggest increased tumor cell phagocytosis." (PMID 41322194, 2025). "For example, there is evidence that the suppression of CD47/SIRPα signaling pathway components leads to the activation of tumor cell phagocytosis by macrophages, and high CD47 expression correlates with low PFS (progression-free survival) and OS (overall survival) rates." (PMID 39941714, 2025). "Using PD‐L1 and CD47 to validate the proof of concept, intratumoral administration of LNPs in orthotopic tumors achieved efficient editing of ICPs, leading to enhanced immune cell infiltration within the tumor microenvironment." (PMID 39888280, 2025). "In addition to CD47, other regulators of phagocytosis in tumor cells, operating via distinct mechanisms, have been identified." (PMID 41243973, 2025). "Hence, the SIRPα-αMSLN LicMAb combines a tumor-restricted blockade of the CD47–SIRPα axis with a specific antitumor response while preventing on-target off-tumor toxicities." (PMID 40402266, 2025). "Notably, macrophages within TMEs enriched with CD47^high tumour cells presented elevated expression of M2 markers, which prompted further investigation." (PMID 41163221, 2025). "Additionally, STING activation by CDG promotes IFN production, synergistically inducing a pro-inflammatory phenotype in TAMs and enhancing M1 macrophage-mediated phagocytosis of tumor cells, thereby significantly improving the efficacy of anti-CD47 blockade." (PMID 40075527, 2025). "Notably, tumor-infiltrating Treg cells are characterized by high expression of immune checkpoint molecules, including PD-L1 and CD47, which contribute to their immunosuppressive function in the tumor microenvironment (TME)." (PMID 41402667, 2025). "CD47 is highly expressed in tumor cells, making it an important player in macrophage phagocytosis." (PMID 40051791, 2025). "RS17 peptide blocked the CD47–SIRPα signaling in 4T1‐tumor‐bearing mice." (PMID 41403915, 2025).
tumor (continued). "Furthermore, co-expression of CD47 with adaptive immune checkpoint molecules such as PD-1 and PD-L1 was significantly elevated, suggesting a pivotal function for CD47 in tumor immune evasion." (PMID 41514569, 2025). "Tumor cells utilize the “don’t eat me” signal transmembrane protein CD47 to evade phagocytosis." (PMID 40075527, 2025). "In murine models of pancreatic necrosis, TRIM28 was shown to regulate CD47 expression through modulation of miR-133a, whereby TRIM28 depletion led to increased miR-133a levels, suppressed CD47 expression, and enhanced macrophage-mediated clearance of tumor cells." (PMID 41303350, 2025). "To test this hypothesis, we first evaluated CD47 expression in ccRCC publicly available gene expression profile data (GEO and oncomine) and found that CD47 mRNA expression was elevated in tumor tissues compared with normal tissues." (PMID 40548645, 2025). "Furthermore, histological analysis confirmed the co-expression of PD-L1 and CD47 on several human tumor tissues, providing a biomarker rationale for patient selection in clinical trials." (PMID 41514569, 2025). "A recent report highlighted a CBD-SIRPαFc conjugate as a novel tumor-targeting CD47 inhibitor." (PMID 40721833, 2025). "However, during the process of immune evasion tumor cells increasingly display “don’t-eat-me” signals, i.e., phagocytosis checkpoints, like programmed cell death 1 ligand 1 (PD-L1, CD274), MHC-I, and CD47, to tune down anti-tumor immune responses." (PMID 40098954, 2025). "Inhibiting L-amino acid transporter 2 (LAT2) or treating tumor cells with LAT inhibitors can downregulate the expression of CD47, enhance macrophage infiltration and phagocytosis of tumor cells, and improve cancer treatment by interfering with LAT2-mediated amino acid uptake." (PMID 40534850, 2025). "They therefore speculated that in this specific context, the prognostic signal of CD47 might be modulated or overridden by a concomitant anti-tumor (M1) immune response, highlighting the microenvironment-dependent nature of its role." (PMID 41514569, 2025). "Additionally, tumor cells overexpress the immune checkpoint CD47, further weakening the phagocytic and cytotoxic functions of macrophages." (PMID 40287972, 2025). "One likely limitation is the high expression of CD47 on non‐tumour cells, including erythrocytes, which may reduce therapeutic specificity." (PMID 41195773, 2025). "These hybrid exosomes, combining properties of tumor-derived CD47 and M1 macrophage exosomes, were loaded with SN38 and MnO2 to induce DNA damage, stimulate innate immunity, and promote immune cell infiltration, leading to significant anti-tumor and anti-metastatic effects." (PMID 40317075, 2025). "This review summarizes current understanding of TAM recruitment, polarization, and pro-tumoral functions in TNBC, and outlines emerging therapeutic strategies aimed at depleting TAMs, reprogramming them to an anti-tumor M1-like state, or blocking the CD47-SIRPα phagocytosis checkpoint." (PMID 41142826, 2025). "In immune checkpoint inhibitor-based therapies, CD47-SIRPα blockers enhance tumor cell clearance through TANs-mediated trogocytosis of antibody-labeled tumor cells, while targeting FcγRIIa (CD32a) and FcαRI (CD89) optimizes antibody-dependent cellular cytotoxicity (ADCC)." (PMID 40568594, 2025). "The dual blockade of CD47 and PD-1/PD-L1 shows synergistic anti-tumor effects." (PMID 40861801, 2025). "M2 TAMs up-regulate the CD47 “don’t eat me” signal, facilitating tumor immune evasion." (PMID 40948940, 2025). "Upon CD47 block, killing of the tumor cells was 11.4% and 11.6% for the Capan-2 cell line." (PMID 40358156, 2025). "Tumor cells overexpress CD47 to inhibit macrophage phagocytosis and immune activation." (PMID 40529368, 2025).
tumor (continued). "Strategies that target CD47, including the use of the anti-CD47 antibody and CD47 knockdown for cancer therapy, demonstrated that CD47 blockade significantly increased macrophage infiltration and phagocytosis, thereby enhancing the anti-tumor response." (PMID 40296909, 2025). "Notably, a US trial (NCT02216409) used anti-CD47 antibodies Hu5F9-G4 in advanced cancers, including those of the SG and head and neck, to enhance Mφ-mediated tumor cell elimination." (PMID 41164198, 2025). "In addition, we observed a similar pattern of lysis in two primary (patient) tumor cell samples with EpCAM IgA mAb (with CD47 blockade)." (PMID 40358156, 2025). "When CD47 and PD-L1 were co-blocked, synergistic anti-tumor effects were observed in certain models, directly demonstrating that modulating macrophage function, among other mechanisms, can alleviate the immunosuppressive state in pancreatic cancer and thereby suppress tumorigenesis." (PMID 41463034, 2025). "Therefore, blockade of CD47 supports the development of anti-tumor immunity by increasing phagocytosis of tumor cells and the presentation of antigen to T cells." (PMID 41322194, 2025). "However, it is unique in that its second arm targets CD47 which is expressed by SCLC to prevent macrophage-mediated destruction of tumor cells." (PMID 40507328, 2025). "CD47 mAbaimed at blocking the CD47- SIRPαinteraction to promote anti-tumour immunity." (PMID 40385641, 2025). "This paradox might reflect dysfunctional or “exhausted” macrophages that express M1 markers but have lost anti-tumor function, possibly due to chronic CD47-SIRPα signaling." (PMID 41514569, 2025). "CD47 is a transmembrane protein overexpressed in hematological malignancies and represents an innate immune checkpoint as it binds to its receptor SIRPα on macrophages inhibiting phagocytosis and favoring the immune evasion of tumor cells." (PMID 40369208, 2025). "Therefore, to maximize the enhancement of macrophage phagocytosis, CD47/SIRPα blockade antibodies can be combined with tumor-opsonizing therapeutic antibodies that mount pro-phagocytic signaling through Fc/Fcγ interactions." (PMID 40136470, 2025). "In resistant tumor cells, CD47 expression is markedly upregulated." (PMID 40003951, 2025). "This dual-targeting strategy has been validated by a CD47/PD-L1 bispecific antibody (6MW3211), which demonstrated potent synergistic anti-tumor efficacy in preclinical models and a favorable safety profile in GLP non-human primate studies, underscoring its clinical translation potential." (PMID 41514569, 2025). "Four percent lysis was achieved in a third tumor sample, which could be enhanced to 14% by addition of CD47 blockade." (PMID 40358156, 2025). "In CRC, this may be particularly relevant in MSI-high tumors, where CD47-mediated suppression of antigen presentation could impair the initiation of adaptive anti-tumor responses." (PMID 41514569, 2025). "Therefore, the prognostic role of the CD47-SIRPα axis should be contextualized in the complexity of the tumor microenvironment and future studies should investigate the relation between AML leukemic cells and every component of tumor microenvironment." (PMID 40369208, 2025). "Also, the choice of therapies such as CAR T cell therapy, CAR M therapy, or SIRPα-CD47 inhibitor should be determined based on tumor types such as solid tumors or hematologic malignancy." (PMID 40050933, 2025). "Therefore, strategies targeting CD47 urgently require enhanced tumor specificity to minimize “off-target” damage." (PMID 41280655, 2025). "In addition, THBS1/CD47 signaling also control tumor perfusion by indirectly regulating tumor blood flow, thereby limiting tumor growth." (PMID 40988744, 2025). "Moreover, CD47 expression is implicated in epithelial–mesenchymal transition (EMT), tumor stemness, and the shaping of the immunosuppressive microenvironment." (PMID 41514569, 2025).
tumor (continued). "Additionally, neutrophil membrane-coated nanoparticles (NM-NPs) inherit the CD47 molecules and membrane protein characteristics of parent cells, extending circulation time by over 5-fold and improving tumor accumulation by mimicking neutrophil chemotaxis." (PMID 40568594, 2025). "However, a significant association was identified between CD47 expression and age (≥ 60 years old), TNM staging, lymph node metastasis, tumor differentiation, and tumor recurrence (p < 0.05)." (PMID 40765033, 2025). "Rational combinations that address both immune suppression and tumour heterogeneity could transform CD47 inhibition from a transient lead into a viable therapeutic path for this intractable malignancy." (PMID 41195773, 2025). "In contrast, recurrent tumor cells show increased CD47 expression." (PMID 41316282, 2025). "The protein levels of p-AKT and CD47 were significantly reduced in tumor tissues dose-dependently." (PMID 40270598, 2025). "Similarly, CD47-SIRPα axis blockade has shown increasing macrophage-mediated phagocytosis of tumour cells, which can complement existing therapies." (PMID 39939997, 2025). "The authors also discovered that metastatic tumor cells tend to express the ligand CD47, an important “don’t-eat-me” signal, which may influence the anti-tumor immunity of MRC1+ CCL18+ macrophages via its corresponding receptor SIRPA." (PMID 40191203, 2025). "However, radiotherapy-induced microRNA can inhibit CD47 expression to promote tumor cells sensitivity to radiotherapy in cervical carcinoma, kidney carcinoma and human alveolar adenocarcinoma." (PMID 40835598, 2025). "The CD47 present in tumor cells interacts with SIRPa receptors in cDC2 in the TME." (PMID 41176596, 2025). "In addition, H101-induced inhibition of CD47 occurs only in tumors due to selective replication of H101 in tumor cells." (PMID 40296909, 2025). "Western blot analysis using tumor lysates showed that rapamycin reduced CD47 protein levels." (PMID 39665172, 2025). "In addition to preventing phagocytosis by DCs, the CD47-SIRPa interaction inhibits the ability of cDC2 to internalize and initiate an immune response to mtDNA released by the tumor cells." (PMID 41176596, 2025). "Macrophages can be induced to phagocytose tumor cells through SIRPα/CD47 blockade." (PMID 40725081, 2025). "Typically, CD47 can allow tumor cells to evade macrophage-mediated elimination; consequently, the use of specific anti-CD47 antibodies can restore this event, and this is the rationale for the anti-CD47 antibody used in tumor therapy." (PMID 40677711, 2025). "To investigate the metabolic consequences of aptamer-siRNA therapy in tumor-infiltrating Treg cells, we performed targeted serum metabolomic profiling in mice bearing liver tumors and treated with saline, anti-PD-L1 aptamer, CD47 siRNA, or the aptamer-siRNA chimera." (PMID 41402667, 2025). "Therefore, the development of anti-CD47 antibodies with minimized RBC binding and toxicity, while retaining potent activity against tumor cells, represents a promising approach for advancing CD47-targeted cancer immunotherapy." (PMID 40578556, 2025). "Moreover, it can downregulate PD-L1 and CD47 expression, thereby enhancing the immune response of immune cells against tumor cells and synergistically enhancing the effects of immunotherapeutic agents." (PMID 40909948, 2025). "However, the importance of the innate immune system in contributing to tumor progression is quickly emerging, especially within the realm of CD47-targeting agents." (PMID 40078999, 2025). "Patient tumor cells were only killed with addition of CD47 blockade in this sample." (PMID 40358156, 2025). "We additionally hypothesized that the addition of liposomal clodronate (LC), which upon intracellular delivery results in apoptosis of mononuclear phagocytes, would abolish the anti-tumor activity of CD47 blockade." (PMID 41171165, 2025).